KDF1 (keratinocyte differentiation factor 1)
Diseases named in the same sentence as KDF1 in open-access papers (continued):
Sharing a sentence is not in itself a finding about the gene and the disease.
tumor (8 papers, 2021 to 2024). "Analysis based on Univariable Cox regression revealed that KDF1 protein level in the tumor tissue of ccRCC patients was associated significantly with both OS and DSS along with the age of the patients, the size of the tumors, Fuhrman grade and tumor stage." (PMID 34136411, 2021). "To confirm the results of immunohistochemistry, we further detected the KDF1 protein level in five LUAD tumor tissue samples in comparison with the paired adjacent non-tumor lung tissues." (PMID 38137415, 2023). "We first examined the level of KDF1 mRNA in LUAD tumor tissues using the data downloaded from TCGA online database." (PMID 38137415, 2023). "The increased KDF1 mRNA in LUAD tumor tissues was also proved by the results of our quantitative RT-PCR analysis, in which the RNA from 30 tumor tissue samples and paired non-tumor tissue samples was used." (PMID 38137415, 2023). "We observed significantly increased KDF1 mRNA in the tumor tissues of LUAD patients compared with that in the controls." (PMID 38137415, 2023). "In contrast, the expression levels of KDF1 in non-tumor lung epithelial cells of 133, 14 and 0 patients were scored 1, 2 and 3, respectively." (PMID 38137415, 2023). "Compared with the normal renal tissue, the expression level of KDF1 in the tumor tissue of ccRCC patients decreased markedly." (PMID 34136411, 2021). "The decreased expression of KDF1 in the tumor tissue was further confirmed by Western blot analysis." (PMID 34136411, 2021). "Analysis based on Speaman coefficient revealed that the expression level of KDF1 mRNA was negatively correlated with the tumor stage (r=-0.221, p=0.0000003, n=530) and Fuhrman grade (r=-0.249, p=0.000000008, n=522)." (PMID 34136411, 2021). "Patients with higher KDF1 in the tumor tissue were found to have longer overall survival and disease-specific survival time." (PMID 34136411, 2021). "In vitro cell experiments and allogeneic tumor transplantation tests were performed to determine the effects of altered KDF1 expression on the phenotype of ccRCC cells." (PMID 34136411, 2021). "The expression level of KDF1 mRNA was found to correlate negatively with tumor grade and tumor stage, and positively with patients’ OS." (PMID 34136411, 2021). "We first analyzed the expression of KDF1 mRNA in the tumor tissue of ccRCC patients by using the data from TCGA database." (PMID 34136411, 2021). "Analysis based on RNA sequencing data from TCGA database showed that the expression level of KDF1 mRNA decreased markedly in the tumor tissues of ccRCC patients compared with that in the normal renal tissues." (PMID 34136411, 2021). "To test this idea, in the present study, we examined the expression of KDF1 in the tumor tissue of ccRCC patients in comparison with clinicopathological parameters." (PMID 34136411, 2021). "In summary, for the first time, the present study investigated the expression and function of KDF1 in the tumor tissue of ccRCC patients." (PMID 34136411, 2021). "Patients with higher KDF1 protein level in the tumor tissues were found to have a longer OS and DSS when compared with patients with lower KDF1 protein." (PMID 34136411, 2021). "In accordance with the results of mRNA expression, KDF1 protein was also found to be down-regulated in the tumor tissues of ccRCC patients compared with that in the normal renal tissues." (PMID 34136411, 2021). "In the present study, we examined the expression of KDF1 in the tumor tissue of ccRCC patients using two cohorts of patients and compared it with the clinicopathological indices of the patients." (PMID 34136411, 2021). "The association between the expression level of KDF1 protein in the tumor tissue of ccRCC patients and patient’s clinicopathological parameters was analyzed based on the score of immunostaining intensity for KDF1." (PMID 34136411, 2021). "The expression level of KDF1 in the tumor tissue was found to correlate negatively with the tumor grade." (PMID 34136411, 2021).
tumor (continued). "In contrast, immunostaining for KDF1 was much higher in most tumor tissues." (PMID 38137415, 2023). "We observed that in most of the non-tumor tissues, immunostaining for KDF1 was very weak." (PMID 38137415, 2023). "We observed that KDF1 was upregulated in LUAD tumor tissues." (PMID 38137415, 2023). "It was found that KDF1 expression correlated positively with the tumor size." (PMID 38137415, 2023). "High expression of KDF1 was related to tumor stage and histological grade." (PMID 35281796, 2022). "The genetic interaction between Kdf1 and more widely studied stratifin proves that KDF1 may be related to tumor progression." (PMID 35281796, 2022). "The results found that the expression levels of ABCG1, HAVCR2, CD14, and TGFA were significantly increased (p < 0.05) in tumor tissue samples compared with para-cancerous control tissue samples, while the expression levels of KDF1 and KITLG were significantly decreased (p < 0.05)." (PMID 35774505, 2022). "The tumor weight and volume were reduced after silencing KDF1." (PMID 35281796, 2022). "The present clinical finding suggested that down-regulation of KDF1 might be involved in the pathogenesis of ccRCC and KDF1 might function as a tumor suppressor." (PMID 34136411, 2021). "Furthermore, decreased ki-67 positive cells were observed in the xenograft tumor tissue derived from the KDF1 overexpression ccRCC cells compared with those xenograft tumors derived from the control ccRCC cells." (PMID 34136411, 2021). "All these suggest that decreased expression of KDF1 is involved in the pathogenesis of ccRCC and KDF1 may function as a tumor suppressor." (PMID 34136411, 2021). "?A3B2 twb 0.24w?>Given that overexpression of KDF1 was found to decrease the proliferation of ccRCC cells in vitro, we suppose that overexpression of KDF1 might also reduce the growth of ccRCC tumor." (PMID 34136411, 2021). "Higher expression level of KDF1 protein was observed in patients with high tumor grade." (PMID 34136411, 2021). "In addition, new tumor event after initial treatment, pathology tumor size stage, the expression level of RCHY1 and KDF1 might also be associated with lymphatic metastasis." (PMID 34343214, 2021). "In the meanwhile, we observed that the level of KDF1, AKT, p-AKT and p-STAT3 and the ratio of Ki-67-positive cells were significantly increased in the tumor tissues derived from KDF1-overexpressing cells." (PMID 38137415, 2023). "Correlation analysis of six prognostic MDGs (ABCG1, KDF1, KITLG, TGFA, HAVCR2, and CD14) and six types of immune infiltrating cells, including tumor purity, B cells, CD8+T cells, CD4+T cells, macrophages, neutrophils, and dendritic cells was performed." (PMID 35774505, 2022). "To investigate the effect of KDF1 on SKOV3 cells’ growth in vivo, we constructed a nude mouse subcutaneous tumor model." (PMID 35281796, 2022). "All these findings suggest that KDF1, which activates STAT3 and the downstream AKT pathway in LUAD, acts as a tumor-promoting factor and may represent a therapeutic target." (PMID 38137415, 2023). "We observed a markedly increased KDF1 protein level in the tumor tissue samples compared to the non-tumor tissue samples, thus proving the results of our immunohistochemistry." (PMID 38137415, 2023). "Results of Western blot analysis indeed showed the decreased expression of KDF1 in ccRCC tumor tissue compared with the non-tumor renal tissue (1 ± 0.25 vs 0.28 ± 0.08, p<0.01)." (PMID 34136411, 2021). "Both the KDF1 mRNA and protein were found to be decreasingly expressed in the tumor tissue of ccRCC patients when compared with the adjacent non-tumor control tissue." (PMID 34136411, 2021). "As KDF1 overexpression has been shown to increase the proliferation of LUAD cells (A549 cells) in vitro, we speculated that overexpression of KDF1 might also enhance LUAD tumor growth in vivo." (PMID 38137415, 2023).
tumor (continued). "As an upregulated KDF1 mRNA level does not necessarily mean an upregulated KDF1 protein level, to determine whether KDF1 protein was also increasingly expressed in LUAD tumor tissue, immunohistochemistry was further performed." (PMID 38137415, 2023).
infection (1 paper, 2023). The state of being infected such as from the introduction of a foreign agent such as serum, vaccine, antigenic substance or organism. "Infection of KDF1-overexpressing A549 cells by Lenti-shKDF1 significantly reduced KDF1 expression in the cells." (PMID 38137415, 2023). "For PC-9 cells, we obtained another cell model, Psh, with stable low expression of KDF1 through Lenti-shKDF1 infection." (PMID 38137415, 2023).
KDF1 also shares sentences with these, for which no sentence is quoted: ectodermal dysplasia (2 papers); clear cell renal cell carcinoma (1); diabetes mellitus (1); Hypertension (1); Oligodontia (1); renal cell carcinoma (1).